NEUROD1 (neuronal differentiation 1)
Diseases named in the same sentence as NEUROD1 in open-access papers (continued):
Sharing a sentence is not in itself a finding about the gene and the disease.
tumor (continued). "However, NEUROD1 is also revealed to express in other tumor cells and play a significant role in tumor progression." (PMID 36313290, 2022). "For the TF NEUROD1, there are currently 19 ChIP-seq data sets available, which have been derived from embryonic stem cells, pancreas beta cell, and the pituitary AtT-20 tumor cell line." (PMID 34193535, 2021). "Finally, based on recent in vivo studies, “NEUROD1-high” tumor cells are also suspected to be sensitive to arginine depletion caused by pegylated arginine deaminase (ADI-PEG 20), which leads to the inhibition of tumor cell growth." (PMID 33718595, 2021). "Each of these subtypes is defined by its inter tumor expression levels of the four key transcription regulators: Achaete–Scute Family BHLH Transcription Factor 1 (ASCL1), Neuronal Differentiation 1 (NEUROD1), POU Class 2 Homeobox 3 (POU2F3), and yes–associated protein 1 (YAP1)." (PMID 33809582, 2021). "The β3-AR-antagonist SR59230A and the SK2-inhibitor ABC294640, were both able to decrease the protein expression levels of the early neuronal differentiation marker NeuroD1 in tumor mass excised from A/J syngeneic mice; however, in the presence of the S1P2-agonist CYM5520, this effect was abrogated." (PMID 31477835, 2020). "ASCL1 and NEUROD1 are both necessary for SCLC tumor survival and disease progression, but regulate different downstream pathways, and whether they are involved in EMT is unknown." (PMID 28212573, 2017). "The aberrant expression of NeuroD1 in GP, although a very rare tumor, could complete the panel of neuroendocrine markers for the diagnosis of these tumors." (PMID 24621010, 2014). "We next investigated whether tumor phenotype could be modified by expression of neurogenic bHLH family protein Neurogenin2 (Ngn2) or Neural differentiation 1 (NeuroD1)." (PMID 25594049, 2014). ",84NGF, and NEUROD1 expression in tumor spheres and tumor-like cells suggests autocrine signaling aiding tumor survival, while BDNF expression in normal slices suggest potential paracrine signaling mechanisms that may contribute to tumor cell migration and survival." (PMID 40917877, 2025). "To assess the similarity between the tumor’s gene expression profile and that of GCPs, we performed hierarchical clustering using a list of genes found to be differentially expressed (Padj < 0.01) in proliferating Math1-positive P7 GCPs compared to postmitotic NeuroD1-positive GCs." (PMID 40854122, 2025). "CU-PC01 tumours display DNPC-like clinicopathological features, including the absence of AR, PSA and PSMA, loss of PTEN and RB, and a lack of NE markers, including SYP, neuronal differentiation 1 (NEUROD1), POU class 2 homeobox 3 (POU2F3) and achaete-scute homolog 1 (ASCL1)." (PMID 38667288, 2024). "Our study showed that NeuroD1 could promote the expression of GPX4, thereby enhancing cell antioxidant capacity and preventing harmful oxidative stress caused by the rapid proliferation of tumor cells." (PMID 38134213, 2023). "Hence, targeting NeuroD1-mediated ferroptosis resistance may be a potential strategy for sensitizing tumor cells to chemotherapy and radiotherapy." (PMID 38134213, 2023). "In addition to regulating the tumor progression, NEUROD1 could be also a drug target in cancer therapy." (PMID 36313290, 2022). "Moreover, POMC, Tpit, and NeuroD1 mRNA showed higher expression in the tumor tissue than NFA, but lower expression than CD, suggesting that expression of 2 types of transcriptional factors might be associated with clinical manifestation." (PMID 28865461, 2017). "First, we performed immunostaining for ASCL1 and NEUROD1 on SCLC tissue samples, collected from the primary tumour site, of 15 patients between 2019 and 2022, and observed that 14 samples were positive for ASCL1." (PMID 40595415, 2025). "Tumour cells with this genotype display a high level of plasticity, with an ASCL1-high/NEUROD1-low phenotype at early-stage disease and a NEUROD1-high/ASCL1-low phenotype in invasive late-stage tumours." (PMID 39567755, 2025).
tumor (continued). "Consistent with our enrichment analysis, transcription factors essential for EEC differentiation—such as NEUROD1 and Aristaless-related homeobox (ARX)—were downregulated in both the murine and human tumor microenvironments (TMEs)." (PMID 41303610, 2025). "The expression of the NEUROD1 transcription factor gene was generally low across all samples, with notable heterogeneity observed in lung and pituitary ACTH-secreting tumor samples." (PMID 40002253, 2025). "Although the molecular landscape of SCLC LN metastases largely resembles that of the tumor of origin, key differences exist in terms of DLL3 and NEUROD1 expression, and in subtype distribution." (PMID 40107154, 2025). "As with NEUROD1 and ASCL1 in their respective subtypes, ATOH1 supports cell viability in ATOH1 subtype tumor cells." (PMID 40305287, 2025). "Although the molecular profile of the LN metastases resembles that of the tumor of origin, key differences exist in terms of DLL3 and NEUROD1 expression." (PMID 40107154, 2025). "Together, these results suggest that lineage-specific TFs are largely expressed in clinical SCLC specimens in a mutually exclusive manner at the tumor level, whereas this principle applies more at the cellular level for ASCL1 and NEUROD1 expression." (PMID 40082639, 2025). "Patient tumor samples co-expressing ASCL1 and NEUROD1 suggest that SCLC-A cells are derived from highly dedifferentiated normal NE cells, while SCLC-AN cells, which co-express both transcription factors, exhibit a higher degree of differentiation." (PMID 41220942, 2025). "In neuroendocrine cells, MYC activates Notch to dedifferentiate tumor cells, promoting a temporal shift in SCLC from ASCL1+ to NEUROD1+ to YAP1+ states." (PMID 40433367, 2025). "Neuropathiazol, a neurogenic inducer, was found to bind MET and upregulate NeuroD1 via the PI3K/Akt pathway, enhancing transdifferentiation and inhibiting tumor growth." (PMID 41225636, 2025). "Clinically, tumor tissue immunohistochemistry (IHC) staining is used to measure the protein expression of four transcription factors (ASCL1, NEUROD1, POU2F3, and YAP1) to identify SCLC subtypes." (PMID 40285610, 2025). "Thereafter, synthesized analysis of both SCLC cell lines and tumor RNA data further suggested that SCLC can be definitively distinguished by the TFs ASCL1, NEUROD1, YAP1 and POU2F3." (PMID 39103941, 2024). "In summary, our study revealed a novel function of NeuroD1 in the transcriptional regulation of GPX4 and demonstrated its critical role in tumor cell ferroptosis resistance through direct binding to GPX4 promoter and activation of its transcriptional activity." (PMID 38134213, 2023). "In one sample, notably, most areas of the cell population co‐expressed NEUROD1 and VIM, while two small clusters of tumor cells expressed NEUROD1 only." (PMID 37789961, 2023). "As to concern clinical and pathological correlations, NOTCH1, NEUROD1, MYCL1, and YAP1 were found significantly correlated with tumor stage." (PMID 36121500, 2022). "It is identified that malignant cells in lymph‐node metastatic SCLC have inter‐patient and intra‐tumor heterogeneity characterized by distinct ASCL1 and NEUROD1 expression patterns." (PMID 36618022, 2022). "These single-cell results confirmed the diversity of tumor cell states in SCLC tumors and the regulatory functions of ASCL1, NEUROD1 and other TFs that shape the states of malignant cells in SCLC patients." (PMID 36195615, 2022).
tumor (continued). "We next performed double staining of ASCL1 and NEUROD1 by immunofluorescence (IF) in FLM3, to investigate potential coexpression in tumor cells, and observed that the vast majority of the cells showed an anticorrelated expression of the two TFs." (PMID 34599169, 2021). "We next analyzed the snRNA-seq to identify the tumor cells that express ASCL1 and NEUROD1, and then integrated this data set with the scATAC-seq using SEURAT34." (PMID 34599169, 2021). "Multi-omics studies integrated subtyping, tumor-origin hypotheses, and immune landscape characterization, supporting biomarkers such as IDH2, NEUROD1, and EZH2, and highlighting heterogeneity." (PMID 42209957, 2026). "The tumor tissues were subjected to IF staining for Ki-67, CC3, and NeuroD1." (PMID 41225636, 2025). "Compared to other molecular subtype CDXs (14 ASCL1 CDXs, 4 NEUROD1 CDXs, and 4 ATOH1 CDXs), ATOH1 CDXs were the most aggressive, taking only 61 days to reach the target tumor volume of 800–1,000 mm2 compared to ASCL1 (75 days, p = 0.0128) and NEUROD1 (95 days, p < 0.0001)." (PMID 40305287, 2025). "Instead, a group of SCLC tumours was identified with low expression of ASCL1, NEUROD1 and POU2F3." (PMID 39567755, 2025). "Notably, SCLC tumour cells expressing ASCL1 and NEUROD1 exhibit neuroendocrine features whereas those expressing YAP1 and POU2F3 exhibit a neuroendocrine low phenotype." (PMID 39567755, 2025). "NEUROD1-driven SCLC (SCLC-N) accounts for ~15% of SCLC cases and is characterized by high NEUROD1 expression, often co-expressed with MYC, which drives rapid tumor proliferation." (PMID 40333678, 2025). "While SCLC with upregulated achaete‐scute family bHLH transcription factor 1 (ASCL1) or neuronal differentiation 1 (NEUROD1) expression is a classic type with a neuroendocrine (NE) feature, other SCLC subtypes lack NE features, making SCLC a highly heterogeneous tumor." (PMID 40620228, 2025). "Consequently, nuclear deprivation of ASCL1 and NEUROD1 via KPNB1 inhibition led to impaired growth of SCLC-A and SCLC-N tumor cells in vitro and tumor shrinkage of ASCL1-driven xenografts in vivo." (PMID 38395864, 2024). "Recent studies demonstrated that MYC activates Notch signaling, driving the temporal evolution of SCLC heterogeneity by conducting the sequential conversion of SCLC tumor cells from an ASCL1- to a NEUROD1- and, ultimately, to a non-NE (YAP1) state." (PMID 38395864, 2024). "Furthermore, clinical data from TCGA and GTEx further confirmed the increase of NeuroD1 and GPX4 in various tumor tissues." (PMID 38134213, 2023). "Furthermore, the conjugate system effectively downregulated the expression of SNAIL, an essential gene in cancer metastasis, and upregulated the expression of the tumour-related genes HNF4 and NEUROD1 under hypoxic conditions." (PMID 37798384, 2023). "While SCLC-N is canonically defined by expression of NEUROD1, characterizing this subtype as a partial-EMT state may lead to new insights regarding its functional role in SCLC tumor progression and metastasis." (PMID 36900269, 2023). "By examining the basal transcriptional programs present in senescing (Type V) and dying (Type D) tumor-derived cells, we determined that Type D and Type V cells have gene expression programs that resemble ASCL1 and NEUROD1 molecular subtypes of human SCLC, respectively." (PMID 37479684, 2023). "Our previous findings demonstrated that positive regulation of G6PD transcriptional activity by various transcription factors (including YY1, NeuroD1, PBX3, and p52-ZER6) enhances tumor cell proliferation by promoting tumor cell nucleotides and lipid biosynthesis." (PMID 38139067, 2023). "To estimate the limit of detection of ASCL1 and NEUROD1 signal in cfDNA, we applied the classifiers to serial dilutions of CDXs representing the three categories and found positive signals for ASCL1 and NEUROD1 down to 3% and 4% tumor fraction, respectively." (PMID 35941262, 2022).
tumor (continued). "In addition, key TFs related to SCLC tumor subtypes, such as ASCL1, NEUROD1, and POU2F3, were found to be differentially expressed in our cohort, as further described in the following sections." (PMID 36195615, 2022). "A recent study described a strong linkage between SSTR2 and NEUROD1 expressions, suggesting that these two markers could coexist in the same populations of the SCLC subtype within the same tumor." (PMID 33809582, 2021). "In accordance with the RNA-seq, the tSNE analysis showed a single cluster of the FLM5 tumor cells with accessibility at ASCL1 promoter but not at NEUROD1." (PMID 34599169, 2021). "In this study, we did not see significant correlation between NeuroD1 and Ki-67 expression in tumor cells." (PMID 30719226, 2019). "While ATOH1 CDXs expressed neither ASCL1 nor POU2F3, ATOH1 was expressed alone (CDX17P) or in combination with NEUROD1 at the transcript and protein levels (CDX25, 78% positive tumor cells; CDX30P, 78% positive tumor cells; CDX17, moderate NEUROD1 expression, 30% positive tumor cells)." (PMID 40305287, 2025). "Since GCG encodes the precursor of GLP-1, the observed reduction in GCG and other key EEC markers (CHGA, NEUROD1, PYY) in tumor tissue, combined with these external clinical data, suggests that EECs and incretin hormones may exert an anti-tumor role in colorectal carcinogenesis." (PMID 41303610, 2025). "In the current study, using TMAs and specimen slides from a relatively large cohort (N = 192) of primary resected SCLC, we assessed the tumor‐derived protein expressions of ASCL1, NEUROD1, POU2F3, YAP1 as well as VIM, a mesenchymal marker which may be a potential assay to define SCLC‐I." (PMID 37789961, 2023). "In addition, ASCL1/NEUROD1 double-negative tumours (14% SCLC) are a distinct subtype of SCLC characterized by low expression of neuroendocrine markers." (PMID 37870696, 2023). "Meanwhile, in another study, the same group also showed that the expression of conventional markers linked with NE differentiation is substantially higher in ASCL1‐ and NEUROD1‐defined tumours (vs. ASCL1/NEUROD1‐double‐negative tumours), which as well corresponds with our findings." (PMID 36149789, 2022). "Notably, we could distinguish the clusters that correspond to the two tumor subtypes based on the differential accessibility to the ASCL1 and NEUROD1 promoters." (PMID 34599169, 2021). "Furthermore, the similarity in terms of the DNA accessibility shown by SCLC and NEPC depends on the status of ASCL1 or NEUROD1 expression but not on the tumor type." (PMID 34599169, 2021). "Gene expression profiling on tumor tissue was previously performed in 15 (47%) patients: ten harbored an inflamed (triple negative, I), three an ASCL1+ (A) and two a neuroendocrine (NEUROD1+, N) molecular profile, as previously reported." (PMID 40537796, 2025). "In our model, we detected NEUROD1 expression in GFP+/c-MYChigh cells, tumor spheres, and the assembloids, but not in whole organoids or organoid slices." (PMID 40917877, 2025). "Tumours that are predominantly positive for MYC are in either POU2F3 or YAP1 subgroups, while MYC negative tumours are mostly in ASCL1 and NEUROD1 subtypes." (PMID 37870696, 2023). "This subtype exhibits the highest levels of immune cell infiltration into the tumor, and is identified by a mesenchymal phenotype and a non-neuroendocrine profile with low or absent expression of ASCL1 and NEUROD1." (PMID 38203275, 2023).
tumor (continued). "The SCLC-P tumor, with no detectable expression of ASCL1 and NEUROD1, consisted of individual cells expressing heterogeneous levels of POU2F3, with half of the cells having no detectable expression of POU2F3." (PMID 36195615, 2022). "To investigate a potential LTF behavior of both TFs in NEPC, we performed SE analysis by H3K27ac profiling of ASCL1 and NEUROD1 NEPCs, and found that all models showed SE activation in common at a number of TFs (INSM1 and NFIB) regardless of the tumor subtype." (PMID 34599169, 2021). "Expression of either Ngn2 or NeuroD1 along with HRasV12/AKT resulted in atypical teratoid rhabdoid tumor like (ATRT like) tumor, a tumor type not previously observed after expression of HRasV12/AKT oncogenes alone." (PMID 25594049, 2014). "Furthermore, upon computational integration of ONS-76 samples malignant NEUROD1+ cells were absent in ONS-76 monolayers and tumor spheroids and only very few were present in the DAOY samples." (PMID 39896075, 2025). "In addition evidence from murine models suggest that ASCL1 rather than NEUROD1 is key to tumorigenesis of SCLC and that over time c-MYC enriched tumor cells arise in this population and drive a switch to a NEUROD1 high state." (PMID 36090051, 2022). "Our data revealed that ASCL1, NEUROD1, and POU2F3 were exclusively expressed in the malignant cells of SCLC tumors, however, YAP1 was mainly expressed in normal epithelial cells rather than tumor cells." (PMID 36195615, 2022). "Importantly, ASCL1 but not NEUROD1 directly regulates well-known SCLC-related oncogenes and is required for tumor formation in vivo of GEMMs." (PMID 30477547, 2018).